CDKN2A (cyclin dependent kinase inhibitor 2A)
Diseases named in the same sentence as CDKN2A in open-access papers (continued):
Sharing a sentence is not in itself a finding about the gene and the disease.
oral cancer (30 papers, 2004 to 2025). "The p16 protein, a crucial cell cycle regulator, is encoded by CDKN2A, another essential tumor suppressor gene that is the third-most commonly inactivated gene in oral cancer." (PMID 41374963, 2025). "A longitudinal study revealed that homozygous deletion of exon 1α of the CDKN2A gene, which encodes the tumor suppressor p16INK4a, is a frequent event in oral carcinomas and can also occur in a subset of precancerous lesions." (PMID 40699851, 2025). "It has also been proposed that CDKN2A chromosomal abnormalities are frequently linked with cyclin D1 gene overexpression in oral cancer." (PMID 35047986, 2020). "Recently, The Cancer Genome Atlas (TCGA) data shows that 57% of HPV-negative HNSCC contains a mutation or loss of the CDKN2A gene, this demonstrates that additional genomic alterations on CDKN2A others than methylation are involved at early events of oral cancer development." (PMID 35154165, 2022). "Patients harboring germline mutations in CDKN2A carry higher risk of oral cancer and melanoma." (PMID 35047986, 2020). "Prior research has similarlyindicated that alterations in CDKN2A are more common in oral cancers, potentially reflecting differences in early carcinogenic pathways." (PMID 40978632, 2025). "Hypermethylation of the CDKN2A promoter region has been extensively evaluated in oral cancers with the frequency of hypermethylation being reported as anywhere from 28% to 86%." (PMID 22645611, 2012). "Ha and Califano noticed that methylation of CDKN2A ranged from 0 to 85 % in oral cancer." (PMID 24782031, 2014). "This study permitted the proposal of 8 salivary biomarkers for oral cancer in patients previously infected with HPV (RPRD2, PSCA, MCM2, CDKN2A, BAK1, HSPA1A, TANK, MAP2K1)." (PMID 37599356, 2023). "Overall, we report frequent changes in tissue ultrastructure and gene hypermethylation of CDKN2A and CDH1 in oral cancer." (PMID 24782031, 2014).
breast tumors (29 papers, 2007 to 2023). "In contrast to breast tumors, high CDKN2A expression measured by RNA-seq analysis in thyroid tumors, did not entirely correlate with elevated p16 expression and lack of CDK4 phosphorylation." (PMID 37964967, 2023). "Among them, the expression of the majority of genes was decreased in tumor samples except for four genes (ATP7B, SLC31A1, PDHB and CDKN2A), suggesting cuproptosis signaling was significantly downregulated in breast tumors." (PMID 36497253, 2022). "Not having been breastfed has been associated with an increase in methylation of the promoter of the tumor suppressor gene CDKN2A (cyclin dependent kinase inhibitor 2A) in premenopausal breast tumors of 639 women (mean age of 57.6 years)." (PMID 31744183, 2019). "The circuit formed by MYC and the pair CDKN2A/CDKN2B also appears very significant in breast tumors, in coherence with the role that MYC amplification has on the enhancement of cell cycle de-regulation." (PMID 26792175, 2016). "While several cell cycle regulators such as CDKN2A (p16), CCNA2, CCNB1, and CCNE2 express at a higher level in AA breast tumors, a unique gene set comprising of PSPHL, CXCL10, CXCL11, ISG20, and GMDS is overexpressed in AA tumor stroma." (PMID 34889737, 2021). "In a previous study, we found a high rate (90%) of concordant LOH between CDKN2A and MTAP genes in primary breast tumors." (PMID 26751376, 2016). "Some authors report higher frequency of CDKN2A promoter methylation in breast tumors, whereas others have not found a difference between malignant and non-malignant breast tissues." (PMID 28403857, 2017). "To test this hypothesis, we investigated associations between rs11515 genotypes and expression of CDKN2A (transcripts, p16INK4a and p14ARF), and CDKN2B in 25 breast tumors (12 from women with the CG genotype and 13 with the CC genotype)." (PMID 26835415, 2015).
dysplasia (29 papers, 2004 to 2025). A usually neoplastic transformation of the cell, associated with altered architectural tissue patterns. "Of the 21 dysplasia samples, CDKN2A loss was found in four samples, MYC amplification in two, and EGFR in one." (PMID 35897137, 2022). "In addition, the methylations of RUNX3 and APC have been closely correlated with an increased risk of disease progression BE to EAC, whereas that of CDKN2A is related to dysplasia, having a potential role as a biomarker in early stages of dysplasia that may lead to progression from BE to EAC." (PMID 41369383, 2025). "Next, we measured the frequency of CDKN2A LoF in 257 BEs that progressed to high-grade dysplasia or EAC (P-BEs), again sequenced for this study or gathered from published datasets." (PMID 39753721, 2025). "Inactivation on CDKN2A serves as the earliest, initiating event in pathogenesis of dysplasia and EAC." (PMID 34870375, 2022). "Although CDKN2A inactivation was identified both in patients with dysplasia/EAC and NDBE." (PMID 34870375, 2022). "Mutations in CDKN2A have been reported in up to 7% of patients with metaplasia, but most reports suggest that mutations are absent in BE from patients without dysplasia or EAC." (PMID 18831746, 2008). "Genomic loss, chromosomal gains and amplifications, mutations, and aneuploidy are observed in BE, and loss of heterozygosity of CDKN2A is reported in 47 – 75% of patients with BE, in the absence of dysplasia or EAC." (PMID 18831746, 2008). "Using routine biopsy tissue, the application of FISH technique for EGFR amplification and CDKN2A deletion distinguished oral squamous cell carcinoma from non-cancerous dysplasia with high specificity, improved diagnostic performance, and identified patients with poorer survival." (PMID 41463200, 2025).
myocardial infarction (29 papers, 2011 to 2026). Gross necrosis of the myocardium, as a result of interruption of the blood supply to the area, as in coronary thrombosis. "It has been shown that in a transgenic mouse model that allows for specific inactivation of the p16ink4 gene (cdkn2a) in cardiomyocytes, cardiac dysfunction caused by myocardial infarction is significantly improved, and scar size is reduced." (PMID 40305307, 2025). "For example, rs10757278 near CDKN2A/CDKN2B has been robustly associated with myocardial infarction (MI)." (PMID 23382687, 2013). "ANRIL (antisense Non-coding RNA in the INK4 Locus (harboring the CDKN2A/B genes)) variants were related to a variety of vascular diseases (myocardial infarction, aortic and intracranial aneurysm), including ischaemic stroke." (PMID 22776031, 2012). "Similar to the PAR of this KIF3A variant, the PAR for myocardial infarction was 21% in individuals with the previously reported rs10757278 variant located in adjacent CDKN2A and CDKN2B genes." (PMID 21912604, 2011). "Variants in the 9p21 region, which includes CDKN2B-AS1 (ANRIL) and CDKN2A/B, were also associated (lead SNP rs1556516, 49.8% frequency, p=4.7×10−16); this locus is involved in cellular senescence and associated with myocardial infarction and peripheral vascular disease." (PMID 29227965, 2017). "Cdkn2a expression is elevated in the myocardium of ischemic cardiomyopathy patients and p16INK4a protein is enriched in cardiomyocytes within ischemic zones of myocardial infarction tissues." (PMID 41526719, 2026). "To identify whether senescent cardiomyocytes contribute to disease pathophysiology post-myocardial infarction, we established a transgenic model in which p16 (CDKN2A) expression was specifically knocked-out in the cardiomyocyte population." (PMID 37090497, 2023). "Since the G allele of rs10757278 may regulate the expression of CDKN2A/2B and/or ANRIL and was closely related to the onset of myocardial infarction, it was reasonable to speculate that the G allele of rs10757278 very likely impacted lipid metabolism." (PMID 36158791, 2022). "Among various SNPs on CHR 9p21, rs1333049 (CDKN2A/B gene) has been reported to be linked to the incidence and development of coronary artery disease (CAD) and myocardial infarction (MI)." (PMID 36553493, 2022).
soft tissue sarcoma (29 papers, 2009 to 2025). A malignant neoplasm arising from muscle tissue, adipose tissue, blood vessels, fibrous tissue, or other supportive tissues excluding the bones. "Referring to tumor suppressor genes, loss of CDKN2A/B has been reported to be associated with poor prognosis in soft tissue sarcomas." (PMID 40141463, 2025). "In this report, we described the CDKN2A c.172C > T nonsense (p.Gln58) LP variant in a 20 years old male with desmoplastic small round cell tumor, which is a rare soft tissue sarcoma typically diagnosed in males during the adolescent period." (PMID 38730621, 2024). "The state of CDKN2A was also employed for the diagnosis of follicular lymphoma as its loss was correlated with poor patient survival, and for soft tissue sarcoma where a poor outcome was also observed with CDKN2A deletion." (PMID 37626750, 2023). "The CDKN2A locus on chromosome 9p21 is frequently mutated or deleted in a variety of carcinomas as well as in soft tissue sarcomas." (PMID 24345474, 2013). "CDKN2A/2B homozygous deletion exclusively occurs in soft tissue sarcoma patients with NTRK1 fusions." (PMID 37567953, 2023). "CDKN2A/CDKN2B DNA copy number aberrations have been reported to be highly prevalent in MPNST, myxofibrosarcoma, and undifferentiated pleomorphic sarcomas and were associated with a poor prognosis in soft tissue sarcomas." (PMID 40548109, 2025). "Notably, CDKN2A/B homo- and heterozygous losses were correlated with decreased overall survival rates in BCOR-altered pediatric soft-tissue sarcomas." (PMID 41155410, 2025). "Advanced adult-type soft-tissue sarcoma, excluding DD-LPS, or bone sarcoma patients, progressing after at least one systemic line, whose tumors overexpressed CDK4, but not CDKN2A at baseline biopsy, were accrued in this single-arm phase II trial (EudraCT number: 2016-004039-19)." (PMID 37875500, 2023).
metastatic melanoma (27 papers, 2009 to 2025). A melanoma that has spread from its primary site to another anatomic site. "Finally, Palbociclib and Vemurafenib were tested in an open-label Phase I-II trial involving patients with stage IIIC or IV BRAF-V600E/K mutant metastatic melanoma harboring CDKN2A loss and wild type-RB1-expression." (PMID 34071228, 2021). "We hypothesized that genetically predisposed individuals such as those who carried a CDKN2A/p16 mutation might share the expression profile with individuals having sporadic metastatic melanoma." (PMID 26694476, 2015). "Melanocytomas typically demonstrate normal findings on four-color for chromosomes 3, 7, 17, and 9p21/CDKN2A, a key feature that differentiates them from metastatic melanomas." (PMID 41303082, 2025). "It has been reported that CDKN2A will be deleted in metastatic melanoma." (PMID 36891324, 2023). "For example, CDKN2A/p16 deletion leads to increased metastatic melanoma after carcinogen exposure." (PMID 34983823, 2022). "However, so far, no studies have addressed the effects of MAPK-directed targeted therapies in patients with BRAF-mutant metastatic melanoma and germline CDKN2A PVs." (PMID 34069952, 2021). "For instance, gene silencing via hypermethylation of the cyclin-dependent kinase inhibitor 2A gene (CDKN2A), a well-known cell- cycle regulator, is described in 19 %-of primary and 33 % of metastatic melanomas." (PMID 40554927, 2025). "Among them, CDKN1A, CDKN2A, CXCR4 and RAD51 were significantly down-regulated in metastatic melanoma when compared with the primary type." (PMID 38070141, 2023).
Ewing sarcoma (26 papers, 2007 to 2026). A small round cell tumor that lacks morphologic, immunohistochemical, and electron microscopic evidence of neuroectodermal differentiation. "Previously, a tumor from a patient with a Ewing's sarcoma with cyclin-dependent kinase inhibitor 2A/B (CDKN2A/B) loss and FUS-ERG fusion was implanted in the right chest wall of nude mice to establish a PDOX model." (PMID 28404944, 2017). "It is not entirely understood why such a discrepancy exists, but the fact that deletion of CDKN2A is the most prevalent mutation associated with Ewing's sarcoma suggests an important role for the alteration in at least a subset of Ewing's sarcoma." (PMID 21052502, 2011). "In the present study, tumor from a patient with a Ewing's sarcoma with cyclin-dependent kinase inhibitor 2A/B (CDKN2A/B) loss and FUS-ERG fusion was implanted in the right chest wall of nude mice to establish a patient-derived orthotopic xenograft (PDOX) model." (PMID 27286459, 2016). "In the present study, a Ewing's sarcoma patient with both FUS-ERG fusion and CDKN2A/B loss was studied." (PMID 27286459, 2016). "We report here significant efficacy of CDK4/6 and IGF-1R inhibitors on a rare Ewing's sarcoma with FUS-ERG fusion and CDKN2A/B loss in a PDOX model." (PMID 27286459, 2016). "Approximately 10–30% of all primary Ewing's tumors exhibit either homozygous or hemizygous deletion of the CDKN2A gene and sometimes also deletion of the CDKN2B gene." (PMID 21052502, 2011). "CDKN2A alterations, especially deletions were more common in Ewing sarcoma." (PMID 37546405, 2023). "However, since a large percentage of Ewing's tumors exhibit deletion of the CDKN2A locus, it is likely that they also harbor deletions in p14ARF." (PMID 21052502, 2011). "Chromosome 9p21 gene copy number in Ewing's sarcoma family of tumour (ESFT) cell lines and primary ESFT has been evaluated using Multiplex Ligation-dependent probe amplification, and the clinical significance of CDKN2A loss and p16/p14ARF expression investigated." (PMID 17533400, 2007). "Since deletion of cyclin-dependent kinase inhibitor 2A (CDKN2A), which is a tumor-suppressor gene and a negative regulator of CDK4/6, was found in this Ewing sarcoma patient's tumor, the efficacy of palbociclib was tested on the PDOX model of this tumor." (PMID 36003796, 2022).